IFNG (interferon gamma)
Diseases named in the same sentence as IFNG in open-access papers (continued):
Sharing a sentence is not in itself a finding about the gene and the disease.
tumor (continued). "Indeed, Detox-iCAF, IL-iCAF and IFNγ-iCAF recruit monocytes and induce a FOLR2+ tumor-associated macrophage (TAM) phenotype, while ECM-myCAF and TGFβ-myCAF promote TREM2+ TAM and NKG2A+ regulatory NK phenotypes." (PMID 38561380, 2024). "Immunological cells in the TME may be influenced by IFNγ, leading to anticancer effects which include killing tumor cells, effector functions, cell migratory rate, proliferation of immune cells, and presentation of antigens." (PMID 38850527, 2024). "Constitutive genetic disruptions in its any component could hurdle thymic Treg development, abrogate inhibitory function of mature Tregs, and a majority of TI-Tregs produce IFNγ, rising to decelerate tumor growth." (PMID 39227959, 2024). "In reverse experiments, CRISPR–Cas9-mediated targeting of FOXO1 in human Lewis Y (LeY) CAR T cells led to a loss of CD62L expression and a reduction in CAR T cell expansion upon extended culture, and impaired production of IFNγ upon co-culture with tumour cells." (PMID 38600376, 2024). "In this study, tumor immunological profiling following bacterial depletion revealed an increase in anti-tumor immune lymphocytic cells (CD3+CD4+IFNγ+, CD3+CD8+IFNγ+, and CD3+IFNγ+), while a decrease in pro-tumorigenic IL17a (IL17a + CD3 +) and IL10(IL10 + CD4 + CD3 +)." (PMID 39044834, 2024). "More tumor-infiltrating CD8+ T cells produce IFNγ and Granzyme B in perhexiline-treated groups." (PMID 39402302, 2024). "Furthermore, cytokines produced by immune cells can modulate the immune response; for instance, interferon gamma (IFN-γ) from activated T cells can enhance PD-L1 expression in tumor cells, affecting the efficacy of ICI." (PMID 39465007, 2024). "We investigated whether the superior tumor cell killing achieved by MCJ KO CD8 CAR-T cells could be due to increasing IFNγ production or cytotoxicity as observed with the OT-I CD8 cells." (PMID 38789421, 2024). "Notably, the presence in the TME of IFNγ and other cytokines produced by activated immune cells, as well as immune-attracting chemokines and tumor secretion of soluble factors, are well-established elements impacting tumor immune infiltration." (PMID 38427670, 2024). "Consequently, AIM2 upregulation likely reprograms the tumor immune microenvironment towards an immune-inflamed condition characterized by increased IFNγ signaling and PD-L1 expression and is reported to be more responsive to ICI treatment." (PMID 38166970, 2024). "IFNγ induces anti-tumor responses through CD4+ T helper cells and CD8+ T cells." (PMID 38928150, 2024). "Therefore, immunotherapeutic drugs can facilitate vascular remodeling by activating tumor-specific immune cells and promoting the secretion of IFNγ." (PMID 39149649, 2024). "PD-L1 has been shown to be upregulated on tumor, stromal and immune cells upon IFNγ release." (PMID 39835115, 2024). "Additionally, it enhances the expression of NKG2D, TNFα, and IFNγ in tumor tissues, hence promoting immune evasion by multiple myeloma cells." (PMID 39346921, 2024). "Tregs can dampen T cell effector function, whereas CD4 helper T cells play a critical role in the development of anti-tumor immunity by assisting in the development of cytotoxic CD8 T cells, secreting anti-tumor cytokines such as IFNγ and TNFα, and stimulating B cell production." (PMID 39104861, 2024). "However, we found that combination Ad-E and αPD-1 mAb treatment increased the percentage of CD3+ T cells, NK cells, and IFNγ+CD8+ T cells in tumor tissues in comparison with the control group." (PMID 39251538, 2024). "Additionally, interferon-alpha response and interferon-gamma response pathways were enriched in the tumor group." (PMID 39093451, 2024). "Neither is it clear why a predominance of IFNγ-producing T cells, normally associated with anti-tumour activity, correlate with increased tumourigenesis." (PMID 39242821, 2024).
tumor (continued). "The upregulation of INCITE genes involved in various inflammatory and IFNγ-related pathways could induce tumor shrinkage in EAC patients." (PMID 38566201, 2024). "Additionally, NK cells can also secrete lymphokines [e.g., interferon-gamma (IFN-γ)] to modulate immune responses, indirectly impeding tumor cell proliferation and metastasis." (PMID 39439794, 2024). "However, PKM2KO CD8 TE cells were unable to fully induce IFNγ expression or control tumor growth, similar to ARS2KO and CD28 mutant T cells." (PMID 38233562, 2024). "To delineate whether the recruitment of CD8+ T cells rely on chemokines secreted from tumor cells, we conducted an in vitro transwell‐based T cell chemotaxis assay using IFNγ‐treated KPC1199 CM." (PMID 39316363, 2024). "Cytokine-armed pyroptosis induces distinct late tumor transcriptome phenotypes with enrichment in multiple immune signaling pathways that inhibit tumor growth, however, IFNγ signaling can also lead to enhanced transcription of several immunosuppressive molecules." (PMID 39737979, 2024). "Similarly, previous studies from our laboratory have also shown that a short-term HS diet induced interferon γ (IFNγ)/Th1-mediated anti-tumor effector immune responses." (PMID 38891044, 2024). "The stimulation of tumor cells by IFNγ boosts some of these effects." (PMID 39237877, 2024). "IFNγ decreases tumour cell growth in different ways, such as through apoptosis and necroptosis, and by inducing tumour cell cycle arrest, enhancing expression of the cell cycle inhibitor proteins p27Kip, p16, or p21 in different cancers, like breast cancer and hepatocellular cancer." (PMID 38339377, 2024). "Additionally, Th1-polarized CD4+ cells release cytokines such as interferon-gamma and tumor necrosis factor-alpha, which improve antigen presentation by dendritic cells and enhance tumor cell recognition." (PMID 39769460, 2024). "The IFNγ-treated tumor cells express both anti-inflammatory and inflammatory molecules, but it was unclear whether this phenotype would inhibit T cell killing or promote more efficient killing." (PMID 38636457, 2024). "At the same time, a higher level of serum IFNγ was observed than the tumor-bearing control group." (PMID 38827732, 2024). "Moreover, the L1CAM-specific CAR T cells were highly activated by increased interferon gamma (IFNG) release and tumor cell cytotoxicity." (PMID 38520648, 2024). "TAMs can exert a killing effect on tumor cells once activated by TNFα and interferon gamma (INF-γ)." (PMID 38483163, 2024). "Anti-tumor M1 macrophages are induced by IFNγ and lipopolysaccharides." (PMID 38474178, 2024). "Interestingly, the broad elimination of tumor macrophages with an anti-F4/80 CAR led to delayed tumor growth and resulted in CAR-derived-IFNg expression, which resulted in immune editing of the tumor in lung, ovarian, and pancreatic cancer models." (PMID 38727262, 2024). "However, the expression of TNFα and IFNγ in the CX3CR1+ subset was substantially lower than the CX3CR1− subset in the tumor." (PMID 38881188, 2024). "Interferon-gamma (IFN-γ) plays a dual-faceted role in tumor progression and immune surveillance." (PMID 38629578, 2024). "For example, immune checkpoint therapy increases interferon gamma (IFNγ) production by PD-1+CD8+ T cells that co-localise with CCR7+ DCs in tumours, which may activate tumour DCs32." (PMID 38267413, 2024). "Given the prominent and essential role of IFNγ signaling in anti-tumor immunity, we hypothesized that over-expression of TP63 facilitates immune evasion of SCC cells by suppressing the IFNγ signaling pathway." (PMID 38509096, 2024). "IFNγ is a pluripotent pro-inflammatory cytokine known to have both pro- and anti-tumour effects." (PMID 39736644, 2024). "Indeed, this fits with the notion that IFNγ needs to be delivered at the right time to the right place to generate more effective anti-tumor immunity." (PMID 39081326, 2024).
tumor (continued). "Further examination of the TME utilizing flow cytometry disclosed that PHA-793887 markedly augmented the secretion of cytotoxic T cell-associated cytokines, including interferon-gamma (IFN-γ), tumor necrosis factor-alpha (TNF-α), and granzyme B (GZMB), within the tumor milieu." (PMID 39676867, 2024). "Thus, in addition to TIL-derived IFNγ, tumor cell-derived IFNβ appears to be another mechanism for controlling PD-L1 expression." (PMID 39469633, 2024). "We then examined the ex vivo ability of tumor infiltrated CD8 cells to produce IFNγ, since loss of MCJ enhances IFNγ secretion but not synthesis." (PMID 38789421, 2024). "In addition, tumor PD-L1 upregulation occurs in response to IFNγ release by effector immune cells, leading to subsequent immune suppression, a process known as adaptive immune resistance, where tumor cells protect themselves from immune attack." (PMID 38433837, 2024). "Tumor-infiltrating lymphocytes, such as natural killer and T helper type 1, are effective components against cancer growth and metastasis in various cancers through the production of interferon-gamma." (PMID 39459558, 2024). "Treatment with the PD-1 antibody alone could reactivate the tumor-infiltrated CD8+ T cells in H22 tumors by increasing the proportions of IFNγ+, TNFα+ and Granzyme B+ (GZMB+) cells within the CD8+ T cell population." (PMID 38684648, 2024). "Besides, cytotoxic factor expressions, such as GZMB and IFNG, were up‐regulated in combination treatment mice, indicating prominent tumor cell‐killing ability." (PMID 39422063, 2024). "Compared with cKO mice, IFNγ+/− cKO mice showed a significant increase in tumor size and weight." (PMID 38167862, 2024). "In addition, the mechanisms associated with IFNγ-mediated upregulation of IRF1 and PD-L1, which triggers tumor evasion of T cell immunity, are also present in tumor-infiltrating myeloid-derived suppressor cells (MDSCs)." (PMID 38396830, 2024). "Research on interactions involving IRF1 could explain more profound mechanisms for such confusing effects of IFNγ on tumor growth." (PMID 38396830, 2024). "In addition to expanded numbers, TDLN tumor-specific cells primed by αCD45-Cyt exhibited a profound increase in IFNγ expression as measured by MFI and the number of IFN-γ+p15E+ cells, whereas IgG-Cyt failed to elicit IFNγ production." (PMID 39112631, 2024). "Approximately two decades ago, Robert Schreibers team discovered that IFNγ and lymphocytes not only protect the host against tumor growth by upregulating MHC class I but also function to select for tumor variants with lower immunogenicity, which can more easily evade immunosurveillance." (PMID 38216787, 2024). "Anti-GITR agonistic antibody therapy reprograms Tregs into anti-tumor Th1-like CD4+ T cells with the expression of IFNγ and the acquisition of cytotoxic activity against tumor cells and converts the immunosuppressive TIME into an immunostimulatory milieu causing tumor regression." (PMID 39227959, 2024). "Additionally, B-MFs contributed significantly to tumor progression by adopting immunosuppressive phenotypes and promoting cancer growth through the suppression of anti-tumor IFNγ+ CD4+ T cells and the induction of FoxP3+ Tregs." (PMID 39457693, 2024). "In addition, indoleamine 2,3-dioxygenase 1 (IDO1), an interferon-gamma (IFN-γ)-induced enzyme, promotes the infiltration of regulatory T cells (Tregs) and MDSCs in the tumor microenvironment (TME)." (PMID 38351314, 2024). "In addition, Breg cells accelerate tumor growth by inhibiting interferon gamma (IFNγ) produced through CD8+ T cells and also differentiate CD4+ T cells into the regulatory T (Treg) cell phenotype by producing transforming growth factor-beta (TGF-β)." (PMID 39456558, 2024). "Considering that IFNγ (Th1 cytokine) and IP-10 (Th1 chemokine) are pharmacodynamic response markers for IL-12 therapy, our results suggest that cytokine mRNA triplet promoted Th1-polarized anti-tumor inflammation." (PMID 39290693, 2024).
tumor (continued). "Thus, IFNγ signaling paired with selective fatty acids naturally facilitates CD8+ T-cell-induced tumor killing." (PMID 39402302, 2024). "Even though NK cells are best recognized for their cytolytic capacity, their ability to secrete cytokines such as IFNγ and TNFα may act as potential drivers of tumor progression." (PMID 38191418, 2024). "To further investigate this, we determined whether colonic tumour epithelial cells respond to exogenous IFNγ." (PMID 39242821, 2024). "Similarly, measles virus exploits its receptors CD150 and CD46 on tumor cells to trigger the immune response, leading to increased IFNγ levels and a favorable immune milieu for tumor clearance." (PMID 38731910, 2024). "Exposure to interferon-γ (IFNγ) during T-cell-mediated immune surveillance leads to an “immunometabolic editing”, whereby tumor cells coordinate the simultaneous activation of FASN and immune checkpoints such as programmed death ligand-1 (PD-L1) to maximize tumor proliferation and immune evasion." (PMID 39349429, 2024). "In a bid to identify true non-responders, SC2 was further subdivided based on two phenotypes: T-cell reinvigoration (assessed by IFNg release) and tumor cytotoxicity (assessed by tumor content decrease, cleaved Caspase-3 increase, GranzymeB and Perforin release)." (PMID 38383563, 2024). "Proliferating T cells also express high level of Ifnγ and Tnfα, indicating they may also possess tumor cytotoxicity." (PMID 38956432, 2024). "IFNγ signaling is an essential part of anti-tumor cytotoxicity." (PMID 39061147, 2024). "Given that PD-1+ TILs display an impaired capacity to produce interferon-gamma (IFN-γ), an essential cytokine required for an effective anti-tumour immune response, their ability to destroy tumour cells is undermined and may lead to tumour immune escape." (PMID 39508576, 2024). "These pathways include tumor necrosis factor alpha (TNFα) signaling, inflammatory response, IL2 and signal transducer and activator of transcription 5 (STAT5) signaling, and interferon-gamma (IFNγ) response, suggesting its involvement in anti-tumor immune response." (PMID 38515213, 2024). "Similarly, lingual denervation in vivo decreased TGFβ and PD-L1 expression and increased CD8+ T-cell infiltration and the expression of IFNγ and TNFα within tumor." (PMID 38324026, 2024). "While IFNγ serves as a pro-inflammatory marker for TB, it alone is not sufficient to trigger TB reactivation or activation; it requires PD-1 depletion in the tumor." (PMID 38254759, 2024). "To identify whether the knockdown of Aurora-A can influence the cytotoxic activity of tumor-infiltrating T cells, we analyzed IFNγ+/CD4+, IFNγ+/CD8+, and TNFα+/CD8+ T cell populations in tumors." (PMID 38291041, 2024). "Moreover, PDL1 is largely induced by IFNγ, which is mainly produced by differentiated effector T cells in the tumor tissue." (PMID 39168971, 2024). "In the tumor, IFNγ stimulates the production of CXCL9 by tumor and stromal cells, resulting in increased infiltration of CXCR3+ (CXCL9 receptor) cytotoxic immune cells (such as CD8+ T cells and Natural Killer cells) into the tumor that promotes its eradication." (PMID 38698860, 2024). "Besides the expression of IFNγ, tumor necrosis factor (TNF)-α and granzyme B was elevated, exhibiting that tumor-infiltrating Blimp1-deficient Tregs were reprogrammed." (PMID 39227959, 2024). "As a measurement of anti‐tumour immune responses we investigated IFNγ levels." (PMID 38602256, 2024). "Furthermore, we suggest interferon-induced expression of HGF in tumor cells triggered by interferon-gamma provided by stromal cells mediates autocrine activation of MET-signaling in tumor cells." (PMID 38386085, 2024). "Upon triple knockdown of exhaustion markers (PD-1, Tim-3, and Lag-3), CAR-T cells, which target the preS1 domain of HBsAg and exhibit the tumor-reactive marker CD39+ (preS1-CAR-T), potently inhibit tumor growth and increase IFNγ secretion in a patient-derived xenograft (PDX) mouse model." (PMID 39075601, 2024).
tumor (continued). "IL32 transcripts were present in all intratumoral Th subsets, though at different levels, with the highest expression in suppressive Treg followed by Th1 Teff, but also in circulating IFNγ+CD4+ Teff (Th1) reactive to the breast tumor antigen mammaglobulin (MAMI)." (PMID 39211051, 2024). "Overall, these data suggest that the IFNγ not only causes inflammatory and anti-inflammatory markers like PD-L1 and MHC-I but also substantial metabolic changes that inhibit proliferation of the tumor cells." (PMID 38636457, 2024). "Tumours cultured ex vivo with IFNγ resulted in similar activation of CCR7+ DCs." (PMID 38267413, 2024). "However, in a mouse model of mammary cancer, mutations in ERβ resulted in reduced infiltration of CD4+ and CD8+ T cells and lower levels of IFNγ within the tumor microenvironment, leading to tumor growth." (PMID 39682229, 2024). "Moreover, inflammatory cytokines IFNγ and TNFα, which are elevated in the serum of tumor-bearing mice, can strikingly stimulate MSCs to produce more G-CSF." (PMID 38690266, 2024). "This study highlighted the significance of early-phase IFNγ after cryo-thermal therapy, which could be a biomarker for better tumor prognosis." (PMID 38827732, 2024). "Chemotherapy drugs can enhance the recognition and presentation of dendritic cells (DCs), activate cytotoxic T lymphocytes to attack tumors, stimulate the release of interleukin-2 (IL-2), IL-4, and interferon-gamma (IFN-γ), and induce anti-tumor immune responses." (PMID 38809459, 2024). "Treatment with the PARP14 inhibitor RBN012579, by enhancing the IFNγ signalling, re-sensitise these tumours to the PD-1 therapy, establishing PARP14 as an actionable target to reverse IFNγ-driven resistance mechanisms to immune checkpoint blockade therapy (Ref." (PMID 39189367, 2024). "Furthermore, a study in hepatocellular carcinoma also suggested that significantly decreased production of IFNγ due to fewer NK cell within tumor was responsible for poor survival." (PMID 38244071, 2024). "IFNγ could induce apoptosis of tumor cells through the caspase pathway and Fas/FasL-induced cell death." (PMID 38167862, 2024). "Mechanistically, the interaction between attIL12-TILs and autologous tumor cells synergized IFNγ production, which in combination with CCKAR downregulation reduced collagen expression through suppression of both TGFβ-stimulated SMAD activation and CCKAR-AKT signaling." (PMID 39574893, 2024). "The A2aR pathway, which is triggered by increased adenosine levels caused by tissue damage and cellular stress, inhibits T cell receptor signaling and IFNγ production through elevated intracellular cyclic AMP adenosine levels that are increased in the tumor microenvironment." (PMID 39684867, 2024). "Thus, all the in vivo data were in line with our in vitro discoveries that dual signaling activation by attIL12-TILs enhanced the IFNγ-dominated tumor microenvironment to suppress collagen expression." (PMID 39574893, 2024). "Moreover, the expression of the critical downstream mediator of IRE1α pathway, XBP1, was also highly associated with the mRNA levels of the indicators of lymphocytes and anti-tumor immunity, including PTPRC (encoding CD45), CD8A, GZMB and IFNG." (PMID 38291473, 2024). "Gene set enrichment analysis (GSEA) further showed hallmarks of anti-tumor immune responses being upregulated in the mDKN01-treated tumors compared to IgG, including interferon-gamma response, interferon alpha response, TNFa signaling via NFkB, and IL-2/STAT5 signaling." (PMID 38659818, 2024). "The results show that EG7 cell treated with DI or 4-OI could significantly increase IFNγ production and LacZ activity in the tumor-T cell co-culture system." (PMID 39349845, 2024). "Notably, IL‐2‐Fc consistently caused the most significant decrease in tumor Tregs compared to ICK at this earlier time point, which translated into IL‐2‐Fc's significantly higher IFNγ+CD8+/Treg ratio in both models compared to controls and ICK." (PMID 38317590, 2024).